VEGFA (vascular endothelial growth factor A)
Diseases named in the same sentence as VEGFA in open-access papers (continued):
Sharing a sentence is not in itself a finding about the gene and the disease.
breast cancer (continued). "Interrupting the expression of S1PR1 could inhibit the growth of human breast cancer cells (MCF-7 and MDA-MB-231) and suppress the angiogenesis of human umbilical vein endothelial cells (HUVECs) via affecting S1PR1/P-STAT3/VEGFA axis." (PMID 34059068, 2021). "Moreover, VEGFA and FGF2, two pro-angiogenesis factors were also transcriptionally stimulated by NF-κB, thus promoting the angiogenesis of breast cancer." (PMID 34350110, 2021). "In addition, the TIMER database showed that S1PR1 and STAT3 had positive connections in breast cancer, and STAT3 and VEGFA were positively connected." (PMID 34059068, 2021). "Another eight ARGs (BCL2, BIRC5, EIF4EBP1, ERO1L, FOS, GAPDH, ITPR1, and VEGFA) were explored, and the author found that these genes not only were significantly associated with overall survival but also could predict distant metastasis-free survival in breast cancer." (PMID 34869345, 2021). "Meanwhile, MiR-1207-5p can target STAT6 to promote breast cancer growth, DNMT1 is a critical factor responsible for DNA methylation modification, VEGFA can trigger aberrant angiogenesis and induce immune evasion, and IGFBP5 is capable of regulating the insulin-like pathway." (PMID 34760687, 2021). "Notably, the transcripts of PEAK1-suppressed MSC factors (i.e., TGFB3, VEGFA and CSF1) were significantly lower within breast cancer stroma (left three graphs)." (PMID 34239043, 2021). "Further, THSWD may inhibit tumor angiogenesis in breast cancer patients by decreasing microvessel density (MVD) and vascular endothelial growth factor-A (VEGF-A) expression." (PMID 34513708, 2021). "In summary, our work demonstrates that suppressing S1PR1 could inhibit the malignant progression of breast cancer, and the regulatory effect is achieved by regulating the S1PR1/P-STAT3/VEGFA pathway." (PMID 34059068, 2021). "In an in vitro endothelial tube-formation assay, the mean size of the endothelial meshes was significantly increased after transfection of breast cancer cells with miR-20a-5p, whereas expression of VEGFA or other angiogenic factors was not influenced." (PMID 32492882, 2020). "CM from both breast cancer cell lines increased the expression of both transcripts, and ezrin depletion inhibited the stimulus-dependent expression of MMP9 mRNA in both cell lines, and VEGFA mRNA expression in MCF-7 cells." (PMID 33086476, 2020). "To uncover the signal pathway mediating IGFBP7 upregulation, we analyzed the expression of Igfbp7/IGFBP7 in EC (bEND.3 cells and HUVECs) upon the stimulation of VEGFA and TGFβ, which can increase IGFBP7 expression in breast cancer and glioblastoma vasculature respectively." (PMID 33505428, 2020). "Additionally, in our study, ACE2 inhibited the phosphorylation of ERK1/2 in breast cancer cells, which revealed that ERK signalling participated in the ACE2-mediated regulation of the expression of VEGFa." (PMID 31023337, 2019). "Indeed, in breast cancer patients a profound molecular relation between HMGA1, FOXM1 and VEGFA has been further highlighted by TCGA analysis, which confirmed a strong enrichment of VEGFA in patients that overexpressed HMGA1 and FOXM1." (PMID 31311575, 2019). "We explored the role of ACE2 in breast cancer angiogenesis and found that ACE2 could inhibit breast cancer angiogenesis and metastasis both in vitro and in vivo and suppress the VEGFa/VEGFR2/ERK pathway." (PMID 31023337, 2019). "Moreover, we show that expression of both miR526b and miR655 is positively correlated with expression of angiogenesis (CD31 and VEGFA) and lymphangiogenesis markers (VEGFC, VEGFD, and LYVE1) in human breast cancer tissue." (PMID 31277414, 2019). "The UALCAN analysis showed that only CXCL12 had a lower expression level in basal-like (triple-negative) breast cancer compared with luminal-like breast cancer, while CXCL5, IDO1, MIF, PTGS2, and VEGFA all had increased expression levels in basal-like breast cancer." (PMID 31293831, 2019).
breast cancer (continued). "Overall, clinical datasets analysis confirmed that VEGFA expression positively correlates with HMGA1 and FOXM1, and that their presence has an impact on breast cancer development, since a signature combining HMGA1, FOXM1 and VEGFA expression is associated to a worse prognosis." (PMID 31311575, 2019). "Thus, we stratified breast cancer samples according to their relative expression levels of HMGA1 and FOXM1, obtaining a significant enrichment in VEGFA expression in patients in which the HMGA1/FOXM1 axis is activated." (PMID 31311575, 2019). "Furthermore, triptolide also possesses anti-angiogenic effect by inhibiting VEGFA expression in human breast cancer MDA-MB-231 and Hs578T cells, and through COX-2 and VEGF down-regulation in human pancreatic cancer Panc-1 cells." (PMID 31719837, 2019). "As an example, in breast cancer, FOXO3 activation correlates with VEGFA downregulation." (PMID 30842454, 2019). "To validate our findings in vivo, we tested whether high VEGFA alone or together with high SOX2, SNAI2 and decreased miR-452 expression might identify prognostic subsets of primary human breast cancers." (PMID 28504716, 2017). "Other top key drivers like VEGFA, GAPDH and PPARG also play a role in breast cancer and obesity." (PMID 29156709, 2017). "Second, both ZEB1 and VEGFA may induce the production of matrix metalloproteinases (MMPs), such as MMP-2 and MMP-9, in breast cancer cells." (PMID 26882471, 2016). "Thus exogenous VEGFA/FGF2 confers resistance to chemotherapeutics through enhancing PI3K/AKT signaling and inhibiting cell apoptosis in breast cancer cells." (PMID 27362808, 2016). "Thus miR-205 binds VEGFA and FGF2 mRNA 3′-UTRs and decreases their expression in breast cancer cells." (PMID 27362808, 2016). "In summary, this study revealed a novel mechanism that NCOA1 potentiates breast cancer angiogenesis through upregulating HIF1α and AP-1-mediated VEGFa expression, which reinforces the rational of targeting NCOA1 in controlling breast cancer progression and metastasis." (PMID 26287601, 2015). "Because VEGFA contains an HRE within its promoter, we tested the effects of DDT and DDT metabolites on transcription of an HRE-luc reporter construct in MCF-7 breast cancer cells." (PMID 22609851, 2012). "Similarly, HIF-2α can selectively upregulate lncRNA RAB11B-AS1, recruit RNA polymerase II to increase the expression of angiogenic factors including VEGFA and ANGPTL4, and encourage the creation of endothelial cell tubes and distant metastasis of breast cancer." (PMID 41614928, 2026). "Therefore, we decided to evaluate the expression levels of β-catenin and VEGFA proteins in the breast cancer stem-like cells transfected or not with miR-204 mimics." (PMID 38392969, 2024). "Indeed, major gene candidates were identified including IL6, VEGFA and MFGE8 that may play important role in the regulation of TME in breast cancer." (PMID 37975220, 2024). "Further analysis revealed that VEGFA and EZH2 were negatively correlated with their respective upstream miRNAs in breast cancer and were significantly overexpressed in breast cancer compared with normal breast controls and indicated poor prognosis of patients with breast cancer." (PMID 35812757, 2022). "Among this PPI network, PTEN, CCND1, VEGFA, CDC42, and EZH2 were ranked as the top five hub genes, which may function as key genes in the m5C regulators-related miRNA–mRNA regulatory network in breast cancer." (PMID 35812757, 2022). "As a m6A reader, YTHDF3 was overexpressed and clinically correlated with breast cancer brain metastases (BCBM), suggesting that YTHDF3 overexpression was indispensable for multiple steps of BCBM through facilitating ST6GALNAC5, GJA1, EGFR, and VEGFA expressions." (PMID 34952600, 2021).
breast cancer (continued). "Rebeca Santaolalla in a study on the breast cancer cells also showed that TLR-4 enhances migration of breast cancer cells, via PI3K/AKT/GSK3β, and promotes transcription of downstream-catenin target genes (MMP7, MMP9, and VEGFA), leading to breast cancer metastasis." (PMID 34904014, 2021). "Additional work has shown that VEGFA expression is enhanced by co-culture of mouse peritoneal macrophages with adipocytes and mammary tumor cells, but did not explore the specific influence of adipocytes on macrophage phenotype and macrophage-derived VEGFA levels." (PMID 32318345, 2020). "Therefore, we aimed to study the association between dietary intake of protein and tumoral expression levels of Ras homologous gene family member A (RhoA), vascular endothelial growth factor-A (VEGF-A), and VEGF receptor-2 (VEGFR2) in primary breast cancer (BC) patients." (PMID 31333806, 2019). "It is also plausible that WSB-1 could regulate the expression of only a selected number of HIF target genes, rather than all HIF-dependent expression, as it is the case in breast cancer, respectively, for co-factors p300 and DEK for GLUT-1 (SLC2A1) and VEGF (VEGFA) expression." (PMID 29540773, 2018). "Finally, we investigated whether there was any link between the expression of WSB1 and HIF targets SLC2A1, VEGFA, CA9, and HK2 in breast cancer patients." (PMID 29540773, 2018). "Moreover, we recently demonstrated that different factors produced by MSCs, such as vascular endothelial growth factor A (VEGF) and IL6, may cooperate in promoting breast cancer cell migration." (PMID 25344915, 2014). "Regarding VEGFA, non-cancer subjects had values ranging between 10 and 36.9 pg/ml preoperatively (mean, 21.145 pg/ml), in contrast to breast cancer patients who showed values between 18 and 108.54 pg/ml (mean, 48.17 pg/ml), a difference which proved to be statistically significant (P = 0.038)." (PMID 23981902, 2013). "In mouse embryo fibroblasts and human vascular smooth muscle cells 1,25(OH)2D induces VEGFA expression through a VDRE in its promoter, yet 1,25(OH)2D can also suppress VEGF-induced vasculogenesis in cultured endothelial cells and in nude mice implanted with MCF-7 breast cancer cells." (PMID 20070897, 2010). "However, we found that the secreted receptor binding-competent and disulfide-bonded dimer of one of the VEGFA isoforms, VEGF121—among the most important HIF-1-dependent regulators of angiogenesis—is impaired but its monomeric form was still secreted by ERO1 KO breast cancer cells." (PMID 33531624, 2021). "Pan-cancer analysis revealed a negative correlation between the expression of STAT3, VEGFA, ESR2, and ABCG2 and breast cancer patient survival." (PMID 41121538, 2025). "It was reported that in breast cancer cell lines, ID1 induces HIF-1α/VEGFA protein expression but not HIF-1α mRNA expression; in addition, ID1 enhances the stability of the HIF-1α protein." (PMID 35163396, 2022). "From analyses of the same three patient breast cancer datasets, we find HIF1A transcripts and its transcriptional targets, CAIX and VEGFA, and G3BP1 (but not NRF2) are all significantly higher in breast cancers that exhibit gain of function or amplified KRAS." (PMID 34294889, 2022). "Moreover, using a dataset of breast cancer patients we show that the co-expression of HMGA1, FOXM1 and VEGFA is a negative prognostic factor of distant metastasis-free survival and relapse-free survival." (PMID 31311575, 2019). "Furthermore, the expression level of VEGFa mRNA, but not VEGFc mRNA, is increased more than 3 folds in NCOA1-overexpressing mammary tumors in Tg(MMTV-NCOA1) × Tg(MMTV-TVA/RCAS-PyMT) mice when compared with that in Ncoa1 WT mammary tumors in Tg(MMTV-TVA/RCAS-PyMT) mice." (PMID 26287601, 2015).
diabetes (963 papers, 2007 to 2026). "In our cross-sectional case–control study, we showed that the rs2010963 VEGFA gene polymorphism is associated with AMI in a Slovenian cohort with type 2 diabetes mellitus." (PMID 39766291, 2024). "Although some studies have found that there is a higher VEGFA level in diabetes, suggesting that the elevated VEGFA levels are pathogenic markers for diabetes." (PMID 35637650, 2022). "The angiogenic factor, vascular endothelial growth factor A (VEGF-A), was associated with diabetes status in our longitudinal cohort." (PMID 32517700, 2020). "Unlike rs6756667 in EPAS1, relationships with the SNP rs3025039 and other VEGFA gene variants have been widely reported for HA illness and for cancer, heart disease, diabetes, neurological diseases and many other types of diseases." (PMID 32718338, 2020). "Myoferlin (MyoF) is a ferlin family member protein located in the plasma and nuclear membrane that plays a major role in VEGFA secretion and causes cardiac muscle weakness in diabetes." (PMID 30212560, 2018). "Inhibition of VEGFA at the onset of diabetes abolished the associated diabetes-glomerular hyperfiltration, glomerular hypertrophy, and urinary albumin excretion in the type I diabetes model." (PMID 28774305, 2017). "More specifically, diabetes is associated with increased levels of glomerular VEGFA expression." (PMID 41300838, 2025). "This suggests that the copper transporter CTR1 may indirectly stimulate the upregulation of VEGFA in patients with diabetes mellitus-associated heart failure, which is cardioprotective." (PMID 38883603, 2024). "This might be compounded by the glucotoxic damage and loss of beta cells in diabetes which would be expected to reduce vascular endothelial growth factor A (VEGFA) secretion from beta cells, which is a known driver of islet vascularisation." (PMID 38814445, 2024). "Men with type 2 diabetes mellitus (T2DM) received intradermal injections of modified mRNA encoding vascular endothelial growth factor A (VEGF-A) or buffered saline placebo (ethical obligations precluded use of a non-translatable mRNA control) at randomized sites on the forearm." (PMID 30787295, 2019). "A key hallmark of diabetes impaired neovascularisation is reduced VEGFA production and sensitivity." (PMID 30206364, 2018). "In this context, our study aimed to investigate SNPs in miRNA regions targeting VEGFA that impair the silencing mechanism, describe the population frequency affected by these alleles, and characterize the physiological effects under the conditions of diabetes complications." (PMID 40427019, 2025). "Similarly, a study reported that VEGFA may increase vascular permeability and promote inflammatory infiltrations causing glomerular disease in diabetes." (PMID 36114523, 2022). "miRNAs are recognized as regulators of the VEGFA gene in the development of diabetes, potentially linking them to the prevention of vascular disorders." (PMID 40427019, 2025). "In insulin-resistant conditions, VEGFA expression appears to be elevated in the circulation, possibly due to the impacts of diabetes and inflammation." (PMID 40427019, 2025). "Among candidate genes, vascular endothelial growth factor A (VEGFA) has been extensively investigated due to its role in endothelial homeostasis and microvascular complications of diabetes." (PMID 41300838, 2025). "Among the top 20 core targets, 5 targets (STAT3, PIK3CA, AKT1, EGFR and VEGFA) were closely related to diabetes." (PMID 38921004, 2024). "Consistent with our data, VEGFa downregulation has been reported in the muscles of individuals with diabetes and is correlated with exercise capacity." (PMID 38856757, 2024). "Clinical trials, such as the randomized phase 1 study (NCT02935712), introduced VEGFA mRNA in healthy volunteers with type 2 diabetes mellitus." (PMID 39204382, 2024). "In patients with diabetes, hypoxia in the wound microenvironment is the main stimulus for the VEGFA uptake into the wound area." (PMID 37982089, 2023).
diabetes (continued). "A change in the microenvironment, usually hypoxia or oxidative stress in diabetes, triggers this cascade of events, promoting the release of the master proangiogenetic molecule, VEGFA." (PMID 37917183, 2023). "In this model, degeneration of the neuroretina is already visible at 2–3 weeks after diabetes induction, while significant vascular alterations, and VEGFA upregulation occur at 6–8 weeks post-injection." (PMID 36291113, 2022). "Meanwhile, the pathways involved in the treatment of diabetes complicated by AS by XFZYD are related to the VEGFA signaling pathway, AKT1 signaling pathway, and CCL2 signaling pathway." (PMID 35960089, 2022). "Vascular endothelial growth factor A (VEGFA) expression is increased during diabetes to protect glomerular microvasculature and nephropathy inhibition." (PMID 35154608, 2021). "Reduced VEGFa signaling and impaired angiogenesis as well as collateral blood vessel formation occur in patients with diabetes mellitus." (PMID 34545676, 2021). "We have shown that HDL rescues diabetes-impaired angiogenesis via the classical HIF-1α/VEGFA signaling axis." (PMID 34483928, 2021). "Both vandetanib and gliclazide are known to target VEGFA, which has shown a clear connection to diabetes pathology and treatment." (PMID 32764756, 2020). "Various clinical studies have shown an elevated intraocular VEGFA levels in patients with retinopathy of prematurity, diabetes mellitus, retinal vein occlusion, and macular degeneration." (PMID 32382040, 2020). "Here, this study was designed to determine the relationship between long non-coding RNA (lncRNA) H19, mircoRNA29b (miR-29b), and VEGFA in the development of diabetes mellitus (DM)." (PMID 31737629, 2019). "We previously found that rHDL rescues diabetes-impaired neovascularisation by augmenting VEGFA production and VEGFR2 signalling." (PMID 30206364, 2018). "In contrast to the levels of Vegfa mRNA in the LV, VEGFA expression in the blood vessel wall was significantly higher in diabetes-exposed Hif1a+/− than in Wt hearts." (PMID 29753320, 2018). "VEGFA levels in the coronary vessels were increased by the combination of Hif1a haploinsufficiency and diabetes exposure." (PMID 29753320, 2018). "In contrast, in diabetic nephropathy, renal VEGFA levels are elevated in experimental models as well as in diabetic patients The upregulation of VEGFA has been proposed as a contributing mechanism to renal dysfunction during the early phase of diabetes." (PMID 28774305, 2017). "Then, our study extends these findings by establishing that endothelial MPs carrying miR-503 interfere with EFNB2 and VEGFA expression in pericytes, further blocking post-ischaemic angiogenesis and vascular integrity under diabetes." (PMID 26268439, 2015). "Genes for matrix proteins were also transcribed at higher levels in diabetes (i.e., fibronectin and collagen IVα1), whereas vascular endothelial growth factor-A mRNA expression was downregulated in both strains." (PMID 22645604, 2012). "Though most studies find an upregulation of vascular endothelial growth factor, we have consistently found downregulation of vascular endothelial growth factor A in STZ-diabetic mice after diabetes durations of 8 to 12 weeks." (PMID 22645604, 2012). "The VEGFA expression was downregulated in the obese with type 2 diabetes mellitus (T2DM)." (PMID 41007804, 2025). "This approach revealed that in diabetic mice, the angiogenic blood vessels within the VEGFA-infused Matrigel exhibited a notable decrease in Dab2 levels compared with those in the WT mice, indicating the impact of diabetes on Dab2 expression and its potential role in angiogenesis." (PMID 39846251, 2025). "It suggests that upregulation of VEGFA in diabetic kidneys protects microvasculature from injury, while decreased VEGFA in diabetes may be detrimental." (PMID 36820318, 2023).